AR (androgen receptor)
Diseases named in the same sentence as AR in open-access papers (continued):
Sharing a sentence is not in itself a finding about the gene and the disease.
prostate carcinoma (continued). "In the prostate cancer cell line LNCaP, WNT3A treatment can promote AR binding to the promoter regions of WNT target genes such as MYC and CYCLIN D1; additionally, AR and β-catenin can be recruited to the promoter and enhancer regions of the AR target gene PSA." (PMID 32678004, 2020). "These mutant proteins in the AR lead to non-specific binding with other steroidal hormones (glucocorticoids, progesterone, and estrogen) that increases AR transcriptional activity resulting in the growth of prostate cancer." (PMID 33303035, 2020). "The terminology “AR-negative prostate cancer” is considered too limiting, while “therapy-related NE prostate cancer” is being discouraged, as it may drive clinicians to withhold potentially effective hormonal therapies." (PMID 33339136, 2020). "Knockdown of either AR or Twist1 did not affect the growth of prostate cancer cells for the short time of the migration assay, excluding the possibility that reduced cell number could be responsible for the reduced cell migration." (PMID 32296610, 2020). "Interestingly, the activity of the proteins coded for by the oncogenes can be inhibited by the polyphenols in both types of prostate cancer, androgen-positive and androgen-negative, without the limitation imposed by the presence of AR." (PMID 30823649, 2019). "In addition, the potential for glucocorticoids to promote rather than to suppress prostate cancer growth has been raised based on the structural similarity to AR." (PMID 31212954, 2019). "Our results suggest that GATA2 directs enzalutamide-induced transcription by recruiting AR, MED1/MED14, and Pol II to regulatory elements of enzalutamide-responsive genes, revealing a novel role of GATA2 in directing antagonist-mediated transcription in prostate cancer." (PMID 31501863, 2019). "Furthermore, high AR levels transcriptionally suppress DNA replication in prostate cancer cells; this activity is increased in CRPC cells expressing high AR levels and is mediated by recruitment of hypophosphorylated RB1; however, AR stimulates also DNA replication through AR hyperphosphorylation." (PMID 31366128, 2019). "YY1 and HDAC4 complex represses HOXB13 gene in AR negative prostate cancer cells." (PMID 31824839, 2019). "Similarly, most cells do not need AR for telomere stability, but our studies have shown a critical role of AR in telomere stability in prostate cancer cells." (PMID 31083651, 2019). "FRG1 expression affects migration and invasion in AR negative prostate cancer cells through known MMPs and cytokines, which may be mediated primarily via p38 MAPK activation." (PMID 30975102, 2019). "Transcriptional repression of HOXB13 in AR negative prostate cancer cells." (PMID 31824839, 2019). "Among them, NCOA3/SRC3 is a co-activator for androgen receptor (AR) and promotes PCa tumorigenesis; DEK acts as a proto-oncogene involved in mRNA processing and DNA replication; ERG is one member of ETS family of transcription factor, and considered as one marker for prostate cancer." (PMID 30237511, 2019). "There is now increasing recognition of phenotypic shifts occurring in metastatic cancers following treatment with AR antagonists resulting in the development of highly lethal, drug-resistant castration-resistant disease such as neuroendocrine (NE) prostate cancer characterised by non-reliance on AR." (PMID 30742096, 2019). "Thus nuclear GSK3ß increases nuclear AR even in the absence of androgens supporting the growth of prostate cancer cells." (PMID 30899444, 2019). "Furthermore, inhibition of AR expression using an siRNA decreased Src activation but not total Src expression in a cellular model of prostate cancer, indicating that AR regulates Src activation but not its expression." (PMID 31537808, 2019).
prostate carcinoma (continued). "Moreover, miRNA-130a, acted like a tumor suppressor, has been reported to inhibit the androgen receptor (AR) and mitogen activated protein kinase (MAPK) pathways and target FOS-like antigen 1 (FOSL1) in prostate cancer, and triple-negative breast cancer, respectively." (PMID 31640738, 2019). "One curious observation is the fact that prostate cancers can maintain transcriptional heterogeneity as a stable phenotype, despite the fact that GREB1 expression drives a feed forward loop which, in principle, should result in an increased fraction of high AR output cells over time." (PMID 30644358, 2019). "PC-3 is androgen receptor negative, representing a model for castrate-resistant prostate cancer." (PMID 31703454, 2019). "Based on our results, CDK5 activation promotes the growth of prostate cancer cells by direct interaction with STAT3 through Ser-727 phosphorylation, while CDK5-mediated STAT3 activation contributes to full AR transactivation in addition to CDK5-dependent Ser81-AR regulation." (PMID 31395805, 2019). "We sought to identify the plausible stemness factor that determines the “molecular signature” of prostate cancer (PCa) cells derived from different metastases (PC3, PCa2b, LNCaP, and DU145) and whether androgen receptor (AR) influences the maintenance of stemness features." (PMID 30206982, 2019). "Interestingly, any of these two events was sufficient to promote the formation of prostate cancer, but only the functional synergy of the oncogenic function of AR and KRAS signaling could promote prostate cancer progenitors in vivo and elevate EZH2 expression." (PMID 31366128, 2019). "In any case, IRC117539 is a remarkable compound that induces selective death of AR-dependent prostate cancer cells regardless of their androgen sensitivity, and may especially be clinically relevant for certain cases of CRPC." (PMID 31431473, 2019). "Interestingly, RSV is able of inhibiting AR-V7 transcriptional activity by downregulating AR-V7 protein levels in ectopically expressed AR-V7 PC3 cells, an AR-negative prostate cancer cell line." (PMID 30832393, 2019). "Thus, identification of alternative pathway dysregulation contributing to PCa progression independent of AR signaling is an active area of prostate cancer research." (PMID 31771198, 2019). "However, bicalutamide, an AR blocker, did not increase the expression of IL-7Rα in AR-positive prostate cancer cells." (PMID 31061414, 2019). "Androgen receptor could regulate the expression of IGF-1 receptor (IGF-1R) via a non-genomic pathway; for example, the re-expression of AR in M12 prostate cancer cells increased IGF-1R expression." (PMID 31126320, 2019). "As the DDB2 expression level is found to be lower in prostate cancer tissues compared to non-neoplastic ones, this could interfere with AR homeostasis and induce subsequent AR-dependent prostate cancer growth." (PMID 31635251, 2019). "Some kinase-related signal transduction pathways can regulate AR transcriptional activities via phosphorylation of AR and AR co-regulators, which may be a main mechanism to maintain AR transcriptional activity in AR-negative prostate cancer cells." (PMID 30367578, 2018). "Effective treatment efficacy in AR negative PC3 line indicates that this strategy may be valuable not only in prostate cancer." (PMID 29861848, 2018). "Neuroendocrine cells do not express AR or PSA, but have markers such as chromogranin A, synaptophysin (SYP), and neuron-specific enolase (NSE) that give NED prostate cancer a distinct biomarker profile and should cause suspicion in cases of metastatic CRPC with low serum PSA." (PMID 29562686, 2018). "Furthermore, ELF5 expression is induced upon AR activation in prostate cancer cells and is a transcriptional target of AR, suggesting a role in negative feedback regulation of AR signaling." (PMID 30200227, 2018).
prostate carcinoma (continued). "Moreover, the effect of metformin treatment was minimal on RWPE-1 and PC-3 prostate cancer cells indicating that lack of AR protein in normal and negative AR cells negates the effects of metformin on cell death." (PMID 30651935, 2018). "Both steroid and non-steroid antagonists treat prostate cancer by blocking AR activity." (PMID 29867496, 2018). "This may reflect distinct transcriptional programs for AR to both evade the effects of ADT and promote metastases, and sheds light on the dynamic interactions of AR to maintain signaling throughout the prostate cancer progression, despite changes in androgen availability." (PMID 30314329, 2018). "However, CRIF1 binding and co-activation of STAT3 may counteract the AR repressor effect of CRIF1, thus sustaining prostate cancer cell growth." (PMID 29914167, 2018). "In the absence of ligand, the AR remains in a non-active state, which forms a protein complex with heat shock proteins (HSPs) and other co-chaperones in prostate cancer, while the AR becomes active when ligand binds, and it translocates to the nucleus as a transcriptional regulator." (PMID 29699584, 2018). "We used hTERT immortalised myofibroblasts transduced with either AR (PShTert-AR), or empty expression vector (PShTert), in co-culture mostly with the AR-negative prostate cancer cell line PC3, so that we could isolate the effect of AR expression to the myofibroblast alone." (PMID 29721186, 2018). "In additional clinical prostate cancer datasets, the overexpression of GPI occurs more frequently in androgen/AR-negative neuroendocrine prostate cancer, suggesting a negative association with the androgen/AR-axis." (PMID 30478344, 2018). "Meanwhile, knockdown of each co-activator led to significant reduction in cell proliferation of AR-positive bladder cancer lines, although, inconsistent with the findings in prostate cancer cells, androgen treatment failed to up-regulate the expression levels of these co-activators in these cells." (PMID 28241422, 2017). "The experimental treatment established in this study is based on the recent discovery that it is the FABP5-PPARγ-VEGF signalling axis, rather than the androgen receptor pathway, played a dominant role in promoting the malignant progression of castration resistant prostate cancer cells." (PMID 28415688, 2017). "Interestingly, AR, whose expression is low in prostate cancer stem cell/progenitors cells, plays a negative role in EMT of these cells, by controlling AKT pathway." (PMID 28430640, 2017). "Interestingly, in AR-negative prostate cancer cells, celastrol is still able to induce autophagy through HIF/BNIP3 activation." (PMID 28664158, 2017). "However the involvement of H2A.Z acetylation during AR signaling in prostate cancer has not been studied yet." (PMID 29116202, 2017). "Concurrent inhibition of AR and non-genomic AR components may prove useful for prostate cancer patients with progression after primary therapy." (PMID 28144231, 2017). "Gal also inhibits the growth of AR negative prostate cancer (PC) cells." (PMID 28881737, 2017). "Our gene expression analyses of androgen-responsive prostate cancer cells exposed to IU1 or USP14 siRNA show a downregulation of PSA but not AR mRNA expression, suggesting that USP14 might not enhance the transcriptional activity of AR." (PMID 28151478, 2017). "Expression of alternative AR isoforms lacking the ligand-binding domain (which normally serves as a binding site for anti-androgens, such as enzalutamide) is associated with ADT resistance in prostate cancer." (PMID 28208703, 2017). "In addition, an inverse correlation between BRCA1 and IGF1R levels was seen in androgen receptor (AR) negative prostate cancer cell lines." (PMID 28706506, 2017).
prostate carcinoma (continued). "Given that ID4 is undetectable or weakly expressed in prostate cancer DU145 cells, they provide an ID4‐negative background as compared to the LNCaP cells wherein ID4 is endogenously expressed, further confirming the domain‐specific interaction between ID4, FKBP52, and AR–protein complexes." (PMID 28252832, 2017). "Furthermore, as PCa is hormonally driven, the crosstalk between AR and VDR in prostate cancer was previously investigated, reporting that AR activation inhibits VDR-mediated transcription through the activity of different coregulatory proteins such as prohibitin, ARA70, or ZNF366." (PMID 28811844, 2017). "Further analysis regarding the mechanisms of the AR complex maturation via REIC/Dkk-3 and SGTA interaction in in vitro and in vivo experiments should contribute to the development of a novel strategy for the treatment of canine androgen-independent prostate cancer." (PMID 28599655, 2017). "Therefore, the correlation of AR and DBB2 expression in prostate cancers seems logical, because high levels of AR expression in cancer cells may activate the DNA repair mechanism that up-regulates DDB2 expression." (PMID 28212551, 2017). "Moreover, the majority of prostate cancer both at primary and metastatic sites are characterized by AR presence regardless of stage and grade." (PMID 29206234, 2017). "The androgen receptor’s ability to switch on genes could be another target for prostate cancer therapy – though not enough was known about the way this ability is regulated and how it controls the progression of prostate cancer." (PMID 28826481, 2017). "It should also be taken into account that HIF-1α/SEPT9_i1 complex (BiFC signal) could be influenced by other cellular functions, such as the androgen-androgen receptor pathway, which does not exist in PC-3 prostate cancer cells." (PMID 28380438, 2017). "Moreover, the distances between M895 and HF are relatively small in these complexes, indicating that M895, together with H12, is near the AR LBD to promote the formation of a coactivator binding site at AF2, which is conducive to transcription to promote prostate cancer cell growth." (PMID 28832499, 2017). "Conjugation of the high-affinity AR agonist RU59063 to the adamantyl group reduced the binding affinity for AR by 37-fold, but led to degradation of AR in LNCaP human prostate cancer cells at low micromolar concentrations, while no AR degradation was seen upon treatment with unconjugated RU59063." (PMID 28298557, 2017). "Our data explored that Exo2 can suppress ERK1/2 activation and proliferation regardless of the presence of AR on the cell, suggesting that Exo2 may have broad anticancer effects on prostate cancer." (PMID 28830537, 2017). "Notably, the inhibitory effects of the candidate chemicals on prostate cancer cell line growth did not appear AR-specific." (PMID 29050220, 2017). "In addition to prostate cancer, growing evidences showed that enzalutamide also exerted anticancer effect on TNBC, which implied that targeting AR might be a good strategy for TNBC." (PMID 29261702, 2017). "Importantly, NFAT inhibitors have been found to decrease viability, inhibit migration and invasion, and enhance apoptosis in prostate cancer cells, independent of the AR status." (PMID 29311926, 2017). "Indeed, in prostate cancer, ASCT2 can be regulated by androgen receptor signalling, and it is therefore possible that pregnancy hormones may also transcriptionally regulate ASCT2 expression." (PMID 28759021, 2017). "Accordingly, forced nuclear localization of Filamin A may terminate non-genomic signals from AR supporting proliferation and restore bicalutamide sensitivity in C4-2 human prostate cancer cells, which exhibit androgen-independent growth." (PMID 28144231, 2017).
prostate carcinoma (continued). "We therefore sought to identify potential pathways that could mediate the effects of warfarin, not just on AR activity, but on chemoprevention of prostate cancer." (PMID 28099154, 2017). "With the use of AR-negative PC-3 human prostate cancer–cell xenografts in the flank regions of mice, post-treatment with oral resveratrol (30 mg/kg/day) decreased the volume of tumors, with lowered tumor-cell proliferation and neovascularization, and induced apoptosis." (PMID 29194365, 2017). "Of interest, DOT1L was recently shown to methylate non-histone proteins like the androgen receptor through recruitment of the PRNCR1 long non-coding RNA for subsequent activation of this receptor in prostate cancer after looping between enhancer and promoter sequences." (PMID 28804523, 2017). "This negative feedback mechanism of the AR signaling pathway might maintain prostate cancer in a well differentiated type of adenocarcinoma." (PMID 28264478, 2017). "Epithelial androgen-independent prostate cancer stem cells or AR negative stem cells have been hypothesized to be present in the prostate cancers which become enriched by androgen deprivation therapy." (PMID 27034170, 2016). "The decrease in cell growth produced by TQ treatment may be AR-dependent as TQ treatment did not have a pronounced effect on the growth of the androgen-independent DU145 human prostate cancer cell line." (PMID 26986969, 2016). "There is much cross-talk between AR genomic and non-genomic pathways in prostate cancer." (PMID 27793987, 2016). "Interestingly, PAC usually contains a small population (usually ~1 %) of scattered neuroendocrine (NE)-like prostate cancer (NEPC) cells that do not express AR and PSA." (PMID 27438705, 2016). "Activated ERK can phosphorylate AR and its co-activators, and therefore, this feedback loop of the non-genomic AR signaling may induce genomic AR signaling in prostate cancer." (PMID 27793987, 2016). "Moreover, miR186 overexpression or knockdown in a AR-negative metastatic prostate cancer cell line PC3 or an AR-positive cell line LNCap also showed the same phenotypes as in M12/P69." (PMID 27121312, 2016). "Importantly, prostate cancer-associated SPOP mutants fail to target AR for ubiquitination, whereas AR splicing mutants lacking hinge domain are refractory to SPOP-mediated degradation." (PMID 27200299, 2016). "Therefore, the purpose of our AR ChIP-Seq study is to further characterize the ARE and identify cooperation with adjacent transcription binding motifs in androgen-responsive and androgen-insensitive prostate cancer cell lines." (PMID 27623747, 2016). "Advances in prostate cancer (PCa) research have led to the development of novel therapies for the metastatic castration-resistance (CRPC) form of the disease, such as two recent drugs abiraterone and enzalutamide, which target the androgen receptor (AR) pathway." (PMID 26813233, 2016). "Although it was shown that dihydrotestosterone (DHT) down-regulated SMP30/regucalcin mRNA expression in prostate cancer LNCaP cells, this inhibitory effect was abolished by flutamide, an AR antagonist, suggesting that down-regulation of SMP30/regucalcin expression by DHT is through AR modulation." (PMID 27553527, 2016). "Collectively, our results suggest that AR up-regulates TIMP2/3, suppresses invasion and migration of prostate cancer cells and inhibits the expression of DANCR; moreover, DANCR impedes the upregulation of TIMP2/3 and the suppression of invasion and migration by androgen-AR signaling pathway." (PMID 27191265, 2016). "Furthermore, PC-1 inhibits AR activity and at the same time promotes prostate cancer progression through a negative feedback mechanism." (PMID 27835608, 2016). "Interestingly, AIL more potently inhibited the growth of AR positive prostate cancer cells than either AR negative tumour cell lines or normal prostate cell lines." (PMID 27959342, 2016).